C10orf120 (chromosome 10 open reading frame 120)
Description:
Dispensable for normal development and fertility.
Synonyms: bA318C4.1
Tractability: No criterion of Open Targets' tractability assessment is met for any kind of drug.
Gene: Protein-coding gene on chromosome 10 (122,697,709 to 122,699,846, reverse strand). Ensembl gene ENSG00000183559.
Gene Ontology:
Molecular function: protein binding
Genetic constraint (gnomAD): Loss-of-function variants: 11 observed, 8.63 expected, observed/expected ratio (o/e) 1.27, 90% interval 0.79 to 1.87. That is too few expected variants to judge how well the gene tolerates losing a copy. Missense variants: 435 observed, 424.39 expected, observed/expected ratio (o/e) 1.02, 90% interval 0.95 to 1.11. Synonymous variants: 140 observed, 144.69 expected, observed/expected ratio (o/e) 0.97, 90% interval 0.84 to 1.11.
Homologues: Orthologues: chimpanzee C10H10orf120 (98% identical), macaque C9H10orf120 (82% identical), dog C10orf120 (61% identical), rabbit C10orf120 (51% identical), rat C1h10orf120 (50% identical), mouse 4933402N03Rik (49% identical), pig C14H10orf120 (38% identical), zebrafish btbd16 (15% identical), Drosophila melanogaster gcl (14% identical), Caenorhabditis elegans gcl-1 (13% identical). Paralogues in human: GMCL1 (17% identical), GMCL2 (16% identical), BTBD16 (15% identical).